GEM (GTP binding protein overexpressed in skeletal muscle)
Description:
Could be a regulatory protein, possibly participating in receptor-mediated signal transduction at the plasma membrane. Has guanine nucleotide-binding activity but undetectable intrinsic GTPase activity.
Synonyms: KIR
Tractability: Small molecule: a structure with a bound ligand is known. Antibody: UniProt places it where antibodies can reach, with medium confidence; its Gene Ontology location is reachable by antibodies, with medium confidence.
Gene: Protein-coding gene on chromosome 8 (94,249,249 to 94,262,461, reverse strand). Ensembl gene ENSG00000164949.
Subcellular location: Cell membrane
Pathways (Reactome):
Gene expression (Transcription): NPAS4 regulates expression of target genes
Gene Ontology:
Molecular function: GDP binding; GTP binding; GTPase activity; magnesium ion binding; protein binding; calcium channel regulator activity
Biological process: chromosome organization; metaphase chromosome alignment; mitotic cell cycle; cell surface receptor signaling pathway; immune response; signal transduction
Cellular component: cytoplasmic side of plasma membrane; midbody; mitotic spindle; spindle midzone; plasma membrane; nucleus
Genetic constraint (gnomAD): Loss-of-function variants: 21 observed, 24.2 expected, observed/expected ratio (o/e) 0.87, 90% interval 0.61 to 1.25. The upper end of that interval is the gene's LOEUF score, 1.25, which puts it in group 5 of 6, group 1 being the genes least tolerant of losing a copy. Missense variants: 313 observed, 361.23 expected, observed/expected ratio (o/e) 0.87, 90% interval 0.79 to 0.95. Synonymous variants: 125 observed, 133.62 expected, observed/expected ratio (o/e) 0.94, 90% interval 0.81 to 1.09.
Homologues: Orthologues: chimpanzee GEM (99% identical), macaque GEM (99% identical), guinea pig GEM (97% identical), pig GEM (97% identical), mouse Gem (96% identical), rabbit GEM (96% identical), dog GEM (95% identical), rat Gem (95% identical), tropical clawed frog gem (81% identical), zebrafish gem (54% identical). Paralogues in human: RRAD (57% identical), REM1 (49% identical), REM2 (44% identical), RIT1 (24% identical), RRAS (23% identical), RIT2 (22% identical), RRAS2 (22% identical), RAP2A (22% identical), RALB (21% identical), RAP1A (21% identical), RAP2B (21% identical), RAP1B (21% identical), and 23 more.
Diseases named in the same sentence as GEM in open-access papers:
GEM is named in the same sentence as 19 diseases in open-access papers, as found by Europe PMC text mining. Sharing a sentence is not in itself a finding about the gene and the disease. The quoted sentences say what the papers report.
viral infection (2 papers, 2021 to 2023). "COL4A1 and GEM are genes involved in viral infection, while NRP1, which encodes neuropilin 1 (Nrp1), serves as an HTLV-1 receptor on target cells but has no reported function on HTLV-1-infected cells." (PMID 37375521, 2023).
candidiasis (1 paper, 2021). Infection with the organism Candida. "Interestingly, we showed that genetic variation in close vicinity of the phagocytosis/phagosome maturation-associated genes ASGR2, LAMP1, RAB42, GEM, ATP6V1B2, and RAB20 are associated with susceptibility to candidiasis." (PMID 33510868, 2021).
diabetes (1 paper, 2024). "Members of the RGK GTPase family (Rem, Ras associated with diabetes [Rad], Rem2, GEM/Kir) are potent inhibitors of L-type calcium currents in the heart and neurons." (PMID 39128715, 2024).
gastric cancer (1 paper, 2024). A primary or metastatic malignant neoplasm involving the stomach. "I with a logFC >1, we generated a gene signature of iGC stage progression (intestinal-type gastric cancer progression signature - iGCPS), composed of APOD, COL1A2, GEM, FSTL1, LUM and SPARC." (PMID 39563861, 2024).
glaucoma (1 paper, 2020). Increased pressure in the eyeball due to obstruction of the outflow of aqueous humor. "We identified several key genes, including BMP1, DMD and GEM, that may be involved in the pathogenesis of glaucoma." (PMID 32953253, 2020). "We also identified three key genes, BMP1, DMD and GEM that might be served as potential biomarkers of glaucoma." (PMID 32953253, 2020).
lung carcinoma (1 paper, 2022). "Our findings indicate that the combination of CEACAM1, TNFSF4, GEM, CD47, VTCN1, and TANlncSig in squamous cell carcinoma can effectively stratify patients by prognosis, highlighting these immune checkpoint receptors as potential therapeutic targets against advanced lung cancer." (PMID 36386809, 2022).
muscular dystrophy (1 paper, 2020). Muscular dystrophy (MD) refers to a group of more than 30 genetic diseases characterized by progressive weakness and degeneration of the skeletal muscles that control movement. "A LASSO regression analysis identified three hub genes: Recombinant Bone Morphogenetic Protein 1 gene (BMP1), Duchenne muscular dystrophy gene (DMD) and mitogens induced GTP-binding protein gene (GEM)." (PMID 32953253, 2020).
neuroblastoma (1 paper, 2015). Neuroblastoma (NB) is the most common solid, extracranial childhood tumor. "Likewise, GEM is a small GTP-binding protein that regulates the morphologically differentiation of neuroblastoma cells and Rho-Rho kinase pathway." (PMID 25944692, 2015).
Obesity (1 paper, 2019). Accumulation of substantial excess body fat. "The genes GEM (GTP-binding protein GEM) and PPP1R13L (Protein Phosphatase 1 Regulatory Subunit 13 Like) are interesting target genes of NF-κB as they can act as novel targets for obesity or related syndrome." (PMID 31013288, 2019).
cancer (2 papers, 2014 to 2024). A tumor composed of atypical neoplastic, often pleomorphic cells that invade other tissues. "Immunohistochemical analysis of 368 tumors from cystectomized patients showed high expression of GEM (P = 0.033; HR = 1.46) and EDNRA (P = 0.046; HR = 1.60) was significantly associated with decreased cancer-specific survival." (PMID 25175477, 2014). "The possible functional roles of EDNRA (endothelin receptor type A) and GEM (GTP binding protein overexpressed in skeletal muscle) in cancer progression and metastasis are currently unclear." (PMID 25175477, 2014).
infection (1 paper, 2023). The state of being infected such as from the introduction of a foreign agent such as serum, vaccine, antigenic substance or organism. "HBZ was previously shown to enhance HTLV-1 infection by activating the expression of ICAM1 and MYOF, and in this study, we found that HBZ upregulates two additional cellular genes involved in infection: COL4A1 and GEM." (PMID 37375521, 2023).
GEM also shares sentences with these, for which no sentence is quoted: tumor (5 papers); breast carcinoma (1); carotid atherosclerosis (1); COVID-19 (1); endometrial cancer (1); endometriosis (1); mesothelioma (1); squamous cell carcinoma (1).